CD68 (CD68 molecule)
Diseases named in the same sentence as CD68 in open-access papers (continued):
Sharing a sentence is not in itself a finding about the gene and the disease.
lymphoma (33 papers, 2009 to 2025). A malignant (clonal) proliferation of B- lymphocytes or T- lymphocytes which involves the lymph nodes, bone marrow and/or extranodal sites. "MYD88, CD79B, and other NF-κB-pathway-related mutations promote IL-10 expression by lymphoma cells, and IL-10 has also been found to express in CD68+ and CD163+ tumor-associated macrophages by double immunostaining analysis." (PMID 36644235, 2023). "In T-DLBCL, a marked proportion of TAMs and lymphoma cells have been shown to express PD-L1, and higher proportions of PD-L1+CD68+ TAMs have been associated with longer survival." (PMID 34439203, 2021). "Immunohistochemical analysis of spleens showed a marked reduction of CD19+ lymphoma cell infiltration with concomitant increase of CD68+ macrophage infiltration after treatment with alemtuzumab and S3 in comparison to vehicle control." (PMID 39603243, 2024). "The lymphoma tissue blocks were labeled with primary antibodies against CD68, FOXP3, and CD8, followed by incubation with Alexa Fluor 488, Alexa Fluor 555 and Alexa Fluor 647 fluorescent secondary antibodies." (PMID 38164148, 2024). "Immunohistochemistry is indispensable in cases in which lymphoma and lupus lymphadenitis are histological differential diagnoses due to the presence of CD68 and MPO-positive histiocytes in KFD." (PMID 39439650, 2024). "Splenocytes obtained from littermate control or lymphoma-bearing donor mice were adoptively transferred into CD68-GFP recipients." (PMID 36970721, 2022). "Patients whose lymphomas revealed a high count of CD68-positive macrophages showed prolonged PFS under R-MCP; the median time to progression in the MCP-arm was 52 months vs. 82 months in the R-MCP group (p = 0.0419)." (PMID 31273513, 2019). "The lymphoma tissue samples were characterized by the significantly higher infiltration of CD68-positive macrophages, which were also typified by RCAS1 immunoreactivity, than in the stroma tissue samples." (PMID 25773455, 2015). "CD68 immunoreactivity was present in 95 % of the lymphoma tissue samples and in 60 % of the stroma samples." (PMID 25773455, 2015). "High CD68 expression in TAMs generally indicates an adverse prognosis in various lymphomas." (PMID 40599139, 2025). "In addition, Bcl-2 expression was higher in CD20+ tumor cells (a lymphoma feature) than in CD68+ macrophages." (PMID 41415285, 2025). "Certain studies indicate that elevated levels of CD68+ macrophages are linked to better patient outcomes when effectively treated with therapies like rituximab, while others point towards a poor prognosis associated with high TAM density in various lymphoma types." (PMID 40599139, 2025). "However, in some cells positive for CD20 and some surrounding cells positive for CD68, including diffuse lymphocyte infiltration in the dermis and subcutaneous layer, there is a possibility of other lymphomas and cutaneous metastases of other lymphomas." (PMID 37000052, 2023). "Staining CAM‐Mφ‐lymphoma specimens with antibodies against CD30, CD68, and CD206 revealed a compartmentalization of the tumor." (PMID 31825135, 2020). "Researchers in those studies primarily used key phenotypic markers such as CD68 and CD163 to detect TAMs, correlating marker expression patterns with clinical outcome in patients with different types of lymphoma." (PMID 29868471, 2018). "Type of infiltrating cells (CD8+ T cells prevalence), absence of hematoxylin bodies, or myeloperoxidase co-expression by CD68 histiocytes in lymph node biopsies from patients with Kikuchi-Fujimoto can be helpful in differentiation between SLE and malignant lymphoma." (PMID 35024942, 2022). "Furthermore, we observed a low percentage of the CD68+ cells in tFL compared with NGCB-DLBCL, indicating a different function of the lymphoma-infiltrating immune cells in the different subgroups." (PMID 35887224, 2022).
lymphoma (continued). "The pathological differential diagnosis includes other metastatic neoplasms, other lymphomas with a large-cell appearance, reactive angioendotheliomatosis, or reactive intravascular histiocytosis, where cells express CD68 in the absence of B-cell markers." (PMID 35621627, 2022). "In addition to CD68 and CD163, S100A9, CCR2, CD32, CD36, and Slan were also critical in the characterization of lymphoma‐specific tumor macrophages." (PMID 33135337, 2020). "The MPs are presumably derived from cryptic CD68+ monocytes, as cultures of purified CD20+ lymphoma cells alone usually do not contain CD68+ cells." (PMID 29868471, 2018). "No Mac387 staining was present in pathologic brain and lymphoma tissues suggesting that the CD68 expressing cells present in those tissues were relatively long lived." (PMID 19333384, 2009). "In addition, we observed the promoting effect of Dox, but not Vinc on phagocytosis of lymphoma cells by macrophages, as the increased levels of CD68+CFSE+ cells were detected in the presence of Dox." (PMID 40896706, 2025). "The direct correlation between number of CD68+ macrophages and Deauville score at interim PET may indicate that lymphomas with higher initial macrophage content are at higher probability of treatment resistance, or that persisting macrophages contribute to residual accumulation of [18F]‐FDG." (PMID 26758564, 2016). "The immunohistochemistry in this case presented positive S100, CD1a, and CD68 markers and negative CD30, discarding other diseases as lymphoma, which was sufficient to confirm the diagnosis." (PMID 39958088, 2025). "The current study demonstrated no positive role of the panel of immunochemistry CD4, CD8, CD68, and MMP with the overall survival of the lymphoma prognosis." (PMID 35083113, 2022). "A detailed immunofluorescence analysis of consecutive sections using costaining against CD30 or CD68 with Prox1, a marker for lymphatic endothelial cells, revealed the absence of lymphatic vessels in L428 CAM lymphomas." (PMID 31825135, 2020). "Negativity for leukocyte common antigen (LCA) and other lymphoid markers (CD3, CD20, CD7, CD4, CD79a, CD30, CD68, PAX5, ALK1, and TdT) rules out malignant lymphoma." (PMID 29914385, 2018). "Besides, immunostaining showed that all neoplastic cells in malignant lymphoma sections were positive for CD3 and negative for CD20 and CD68, indicating that the malignant lymphomas were of T-lymphocyte origin." (PMID 28807016, 2017).
Sepsis (32 papers, 2007 to 2025). Sepsis is defined as life-threatening organ dysfunction caused by a dysregulated host response to infection. "iRhom2 deficiency reduces mortality after CLP and decreases CD68+ macrophage infiltration and proliferation in the early stage of sepsis-induced ALI." (PMID 39134731, 2024). "Our results could reflect an exaggerated microglial activation caused by sepsis, as is shown by CD68-immunostaining, in addition to the effect of aging which is expressed by the MHC-class II immunoreactivity." (PMID 17224051, 2007). "Immunostaining for macrophage marker CD68 showed increased positive staining in acute and prolonged sepsis." (PMID 39821755, 2025). "To investigate the role of macrophages in sepsis, we analyzed the CD68+CD206+ macrophage subpopulation (M2) in the PBMCs of septic patients." (PMID 41143725, 2025). "To elucidate the mechanism underlying the effect of iRhom2 on immune cell density in sepsis-induced ALI, we examined the proliferative activity of CD68 + macrophages and CD3+ T cells." (PMID 39134731, 2024). "In a study of obese rats, researchers isolated CD45+/CD68+ATRMs from AT and subsequently cultured them under LPS-mimicking sepsis conditions." (PMID 38027963, 2023). "Colocalization analysis of Iba1 and CD68 showed an increase of activation marker CD68 per microglia in the hippocampus during experimental sepsis." (PMID 37235660, 2023). "Immunostaining of a marker for microglia (CD68) was higher in brain tissues of patients who died of sepsis, supporting that neuroinflammation occurs after the onset of sepsis." (PMID 35488237, 2022). "The activated microglia marker, CD68, was reported to be significantly increased in sepsis patients, while the microglia morphological heterogeneity marker irrespective to activation, MHC-II, was not altered." (PMID 32457609, 2020). "Obese mice with the GLN administration after sepsis showed significantly lower CD68 at 48 h and EMR-1 at 24 and 48 h after CLP." (PMID 33223959, 2020). "In the muscular layer of the small intestine, blocking IL-17A ameliorated sepsis-induced inflammation, as evidenced by a decreased number of CD68+ macrophages and decreased levels of MPO activity." (PMID 31531179, 2019). "In the validation study, patients with sepsis had a significantly higher number of CD-68 positive cells in hippocampus (1.5 fold; p = 0.012), putamen (2.2 fold; p = 0.008) and cerebellum (2.5 fold; p = 0.011) than control patients." (PMID 31384283, 2019). "CD68+ cells were found at higher levels in the sepsis group as compared to leptospirosis and control groups." (PMID 31114579, 2019). "Microglia activation in SAE has been well documented in an autopsy study, which showed a significantly increase in the expression of CD68 in both the cortex and white matter of patients dying from sepsis." (PMID 26924896, 2016). "in patients who died with sepsis there was a significant increase in activated microglia in the grey matter when stained with CD68 compared to controls." (PMID 17224051, 2007). "In 9 of the 13 sepsis patients (69%) a diffuse distribution of CD68 immunoreactivity with a high number of positive cells with an amoeboid (or macrophage-like) appearance was observed in the cortex." (PMID 17224051, 2007). "In this model having sepsis had a significant and independent effect on microglia activation when CD68 positive cells were observed in both grey and white matter (p = 0.009 and p = 0.013 resp)." (PMID 17224051, 2007). "When we investigated the effects of sepsis and age in an ordinal regression model for CD68 immunoreactivity there was a independent and significant effect of sepsis on microglia activation next to the effect of age." (PMID 17224051, 2007). "The parameter estimates of respectively age and having sepsis were 0.069 and 2.329 in the model for CD68 in grey matter." (PMID 17224051, 2007). "During sepsis, CD68-positive cells accumulate in cardiac tissues." (PMID 40872501, 2025).
Sepsis (continued). "We found an enhanced soma size of Iba1-positive cells and an increase of the lysosomal and activation marker CD68 in the CA1 region of hippocampal tissue in the sepsis cohort, whereas the proportion of Iba1-positive cells was unchanged, comparable to previous studies." (PMID 37235660, 2023). "Results of double immunofluorescent staining of iNOS with the marker CD31 for adrenal vascular endothelial cells or the AGRM marker CD68 in LPS-induced sepsis demonstrate that iNOS expression is upregulated in adrenal vascular endothelial cells and CD68+AGRMs rather than adrenocortical cells." (PMID 38027963, 2023). "CD68 mRNA increased with sepsis in skeletal muscle of patients and animals (p < 0.05)." (PMID 35017615, 2022). "To establish whether sepsis and disuse would alter the population of macrophages (CD68+ cells) we performed immunohistochemistry in SOL and EDL sections." (PMID 34309237, 2021). "There was a significant overlap between CD68 and CSN6, and these data showed CSN6 expression in macrophages in a model of sepsis." (PMID 40595050, 2025). "There was a significant overlap between CD68 and CSN6, suggesting that CSN6 expression occurred in macrophages in the sepsis model." (PMID 40595050, 2025). "A consequence of renal injury due to sepsis recruitment of M1-type macrophages was increased CD8 and CD68 count, which showed a significant progressive increase along the experimental period and was the highest at 72 h." (PMID 39949667, 2025). "In our acute CLP induced sepsis model, increased neutrophil infiltration was found 6 h after CLP in myocardium but few macrophages were visualized as stained by CD68." (PMID 39726718, 2024). "In this study, kidney expression of CD68 and EMR-1 was elevated and MPO activity was increased in the obese groups with sepsis, suggesting that macrophage and neutrophil infiltration and inflammation occurred during the experimental period." (PMID 33859538, 2021). "In the pilot study, patients with sepsis tended to have higher density of MHC-II and CD-68 positive microglia in the basal ganglia (putamen, caudate nucleus and globus pallidus) and of MHC-II positive microglia in the hippocampus." (PMID 31384283, 2019). "Post hoc comparisons showed that the expressions of CD68 and CD16 (M1 microglia markers) were markedly increased in sepsis mice (p < 0.05), which were reversed by clenbuterol treatment (CD68: p < 0.05; CD16: p < 0.05)." (PMID 31354429, 2019). "Two cases in which sepsis or significant infection was documented had mean CD45, CD68 and CD163 counts of 31.8, 28 and 33 cells/mm, respectively." (PMID 24402186, 2014). "Two cases in which sepsis or significant infection was documented (cases 22 and 8) had mean CD45, CD68 and CD163 counts of 19.3, 27.4 and 34.1 cells/mm, respectively." (PMID 24402186, 2014). "Subsequent IHC for the neutrophil marker MPO, macrophage marker CD68, and pan-T cell marker CD3 was performed on lung TMA slides to detect changes in the infiltration of these immune cells in the early stage of sepsis-induced ALI before histologic damage was observed (respectively)." (PMID 39134731, 2024). "Cd68 mRNA levels in the lung did not change during the onset and progression of sepsis, nor was it affected by sham surgery, which was corroborated by immunohistochemistry." (PMID 39200137, 2024). "The number of macrophages (CD68+ F4/80+) in lung tissue of CLP-induced sepsis mice was notably increased, and ADMSC-exosomes could effectively reduce the number of macrophages (CD68+ F4/80+)." (PMID 35013123, 2022). "None of the 30 correlations tested were significant for the ARS and counts of either MHC-II or CD-68 positive microglia in any brain region, not in the sepsis or control group separately, nor in both groups combined." (PMID 31384283, 2019). "The higher CD-68 positive microglia counts in sepsis patients in the caudate nucleus and globus pallidus were not significantly different from those in controls." (PMID 31384283, 2019).
Sepsis (continued). "There was also a strong correlation between renal tissue iron overload with iNOS upregulation iNOs/Arg1 ratio, CD8+, CD68+, and CD163+ macrophage phenotype, indicating the impacts of both iron overload and inflammatory macrophages on each other within 72 h of induction of sepsis." (PMID 39949667, 2025). "While the administration of shSCR hMSCs resulted in a decrease in the infiltration of neutrophils (Ly6G+) and macrophages (CD68+) into splenic tissue during sepsis, this decrease in innate immune cell infiltration was not evident in mice receiving shSDC2 hMSCs." (PMID 34355516, 2022).
Alzheimer disease (28 papers, 2009 to 2025). A progressive, neurodegenerative disease characterized by loss of function and death of nerve cells in several areas of the brain leading to loss of cognitive function such as memory and language. "Systemic infection in Alzheimer’s disease was associated with decreased CD68, CD16 (FcγRIII) and increased CD64 (FcγRI) proteins." (PMID 30193587, 2018). "In contrast, the presence of HLA-DR (involved in antigen presentation and identified as a genetic risk factor for Alzheimer’s disease) and phagocytic activity (CD68 and MSR-A) is detrimental to the brain, either by promoting or responding to neuronal damage." (PMID 27256292, 2016). "Interestingly, post-mortem analyses of the middle temporal gyrus in Alzheimer’s disease demonstrated that the state of dementia was positively associated with CD68 microglia marker expression while negatively correlating with IBA-1." (PMID 37457817, 2023). "Elevation of CD68 was also found in the brain of PM2.5-exposed Alzheimer's disease prone mice together with other cytokines and chemokines." (PMID 40319735, 2025). "TLR3 expression has been positively correlated with plaques in Alzheimer disease as well as colocalising with the phagocytic marker CD68." (PMID 36120803, 2023). "Similar to CD68+ microglia observed in patients with Alzheimer’s disease and LPS-induced central neuroinflammation, CD68+ macrophages are abundant in the peripheral nervous system of Nmnat2V98M/R232Q mice, indicating that CD68+ macrophages are activated." (PMID 36287209, 2022). "In the brain, Alzheimer’s disease and memory-related genes (Camk2n1, Apod, and Serpina3n), and immune-response-related genes (Spp1, CD68, GFAP, Mpeg, Ddx3y, Lyz2, CTSZ, Tyrobp, C4b, and C1qa), were selected for mRNA qPCR analysis in adenine-induced CKD mice." (PMID 35447931, 2022). "In Alzheimer’s disease, CD68 stained positive in bloated cytoplasmic processes of dystrophic microglia and in direct vicinity of amyloid-β plaques." (PMID 34571885, 2021). "Cd68 (macrosialin) is a cell surface receptor that is upregulated in phagocytic microglia and in Alzheimer’s disease." (PMID 30413160, 2018). "In Alzheimer's disease, CD68 (p = 0.026), CD64 (p = 0.002), CHI3L1 (p = 0.016), IL4R (p = 0.005) and CCR2 (p = 0.010) were increased independently of systemic infection." (PMID 30193587, 2018). "Up-regulated CD68 expression in microglia has also been observed in various kinds of neurological diseases, such as Parkinson’s disease, Alzheimer’s disease, Pelizaeus-Merzbacher disease and brain tumor, which involves in neurodegeneration, neuronal death and neuroinflammation." (PMID 34168556, 2021). "Notably, TMEM119, as a distinctive marker of microglia, was expressed exclusively on a subset of Iba1+ CD68+ microglia with ramified and amoeboid morphologies in the brains of neurodegenerative diseases, such as Alzheimer's disease (AD)." (PMID 32377265, 2020). "While we included leptin, IL-6, IL-1β, TNF-α, and CRP, we did not assess other cytokines such as MCP-1, IL-18, or markers of microglial activation and phenotype (e.g., CD68 and sTREM2), which may play significant roles in glial reactivity in Alzheimer's disease." (PMID 40521397, 2025). "This reveals not only changes in expression of the gene for the phagocytic protein CD68, tested with immunohistochemistry in the present study but also even greater changes in Trem2 expression, a gene shown in humans to be important in Alzheimer's disease in GWAS." (PMID 30555043, 2019). "In neuroinflammation animal models including cortical demyelination, Alzheimer’s disease, and peripheral nerve injury, COG112 was shown to reduce CD68+ macrophage recruitment." (PMID 25642353, 2013).